GRID1 (glutamate ionotropic receptor delta type subunit 1)
Description:
Member of the ionotropic glutamate receptor family, which plays a crucial role in synaptic organization and signal transduction in the central nervous system. Although it shares structural features with ionotropic glutamate receptors, does not bind glutamate as a primary ligand. Instead, forms trans-synaptic adhesion complexes with presynaptic neurexins and cerebellins, regulating NMDA and AMPA receptor activity and influencing synaptic plasticity through signal transduction (By similarity). In the presence of neurexins and cerebellins, forms cation-selective channels that are proposed to be gated by glycine and D-serine (By similarity). However, recent research disputes this ligand-gated cation channel activity. Cation-selective ion channel can be triggered by GRM1 in dopaminergic neurons (By similarity). Also acts as a receptor for GABA, modulating inhibitory synaptic plasticity through non-ionotropic mechanisms.
Synonyms: GluD1; KIAA1220; GluD1-b
Tractability: Small molecule: a structure with a bound ligand is known; it belongs to a druggable protein family. Antibody: UniProt places it where antibodies can reach, with high confidence; UniProt predicts a signal peptide or a membrane-spanning region; its Gene Ontology location is reachable by antibodies, with medium confidence. PROTAC: its protein half-life has been measured.
Gene: Protein-coding gene on chromosome 10 (85,599,552 to 86,366,795, reverse strand). Ensembl gene ENSG00000182771.
Subcellular location: Postsynaptic cell membrane
Gene Ontology:
Molecular function: G protein-coupled receptor activity involved in regulation of postsynaptic membrane potential; GABA receptor activity; protein binding; signaling receptor regulator activity; AMPA glutamate receptor activity; transmitter-gated monoatomic ion channel activity involved in regulation of postsynaptic membrane potential; identical protein binding; ligand-gated monoatomic ion channel activity; monoatomic ion channel activity; signaling receptor activity
Biological process: negative regulation of synaptic plasticity; phospholipase C-activating G protein-coupled receptor signaling pathway; synaptic signaling via neuropeptide; trans-synaptic signaling by trans-synaptic complex, modulating synaptic transmission; modulation of chemical synaptic transmission; social behavior; synaptic transmission, glutamatergic; ionotropic glutamate receptor signaling pathway; monoatomic ion transmembrane transport; monoatomic ion transport; regulation of postsynapse organization; regulation of postsynaptic membrane neurotransmitter receptor levels; regulation of postsynaptic membrane potential; regulation of synaptic plasticity; signal transduction
Cellular component: extracellular exosome; postsynaptic membrane; synapse; AMPA glutamate receptor complex; dendritic spine; postsynaptic density membrane; trans-synaptic protein complex; GABA-ergic synapse; glutamatergic synapse; membrane
Genetic constraint (gnomAD): Loss-of-function variants: 25 observed, 87.34 expected, observed/expected ratio (o/e) 0.29, 90% interval 0.21 to 0.4. The upper end of that interval is the gene's LOEUF score, 0.4, which puts it in group 1 of 6, group 1 being the genes least tolerant of losing a copy. Missense variants: 1,063 observed, 1,316.1 expected, observed/expected ratio (o/e) 0.81, 90% interval 0.77 to 0.85. Synonymous variants: 534 observed, 534.93 expected, observed/expected ratio (o/e) 1, 90% interval 0.93 to 1.07.
Homologues: Orthologues: chimpanzee GRID1 (99% identical), macaque GRID1 (99% identical), pig GRID1 (99% identical), dog GRID1 (99% identical), mouse Grid1 (98% identical), rat Grid1 (98% identical), rabbit GRID1 (96% identical), guinea pig GRID1 (89% identical), tropical clawed frog grid1 (85% identical), zebrafish grid1a (74% identical), zebrafish grid1b (72% identical), Drosophila melanogaster CG11155 (23% identical), and 38 more. Paralogues in human: GRID2 (56% identical), GRIK1 (26% identical), GRIK3 (26% identical), GRIK2 (25% identical), GRIA4 (25% identical), GRIA1 (25% identical), GRIA3 (25% identical), GRIA2 (25% identical), GRIK5 (24% identical), GRIK4 (24% identical), GRIN1 (21% identical), GRIN2A (18% identical), and 5 more.